RN7SL762P (RNA, 7SL, cytoplasmic 762, pseudogene)
Gene: Miscellaneous RNA gene on chromosome 3 (120,110,498 to 120,110,786, reverse strand). Ensembl gene ENSG00000244308.
Homologues: Orthologues: chimpanzee Metazoa_SRP (99% identical), macaque Metazoa_SRP (90% identical). Paralogues in human: RN7SL1 (82% identical), RN7SL2 (82% identical), RN7SL3 (81% identical), RN7SL113P (78% identical), RN7SL597P (78% identical), RN7SL658P (78% identical), RN7SL126P (77% identical), RN7SL45P (77% identical), RN7SL732P (77% identical), RN7SL408P (77% identical), RN7SL748P (77% identical), RN7SL7P (77% identical), and 701 more.